INS (insulin)
Diseases named in the same sentence as INS in open-access papers (continued):
Sharing a sentence is not in itself a finding about the gene and the disease.
hepatoma (continued). "It has been shown previously using a broad spectrum of liver cell lines and hepatoma cells that ER-stress impairs insulin signalling by depleting the insulin receptor on the cell surface." (PMID 37020593, 2023). "In a recent study, it was reported that insulin induced the phosphorylation of PDHA1 at Ser293 in HepG2 hepatocellular carcinoma cells through the RhoA/ROCK/GSK-3β signalling pathway." (PMID 37761999, 2023). "Here, to determine the effect of Fet-A on insulin signaling in HepG2 human hepatoma cells, confluent cells were treated with varying concentrations of recombinant Fet-A." (PMID 35522655, 2022). "Conclusively, insulin increases cancer cell proliferation/migration and tumorigenesis of hepatocellular carcinoma cells." (PMID 35740278, 2022). "Recently, we reported that insulin induces an increase in p-Ser293 PDHA1 along with p-Ser473 Akt levels in HepG2 hepatocellular carcinoma cells." (PMID 35740278, 2022). "OA, on the other hand, has been reported to significantly inhibit IL-6 levels in insulin-resistant human hepatoma (HepG2) cells and inhibit the secretion of IL-6 from differentiating 3T3-L1 adipocytes." (PMID 36558948, 2022). "This difference was subsequently confirmed when we compared AKT phosphorylation across the three hepatoma cell types, with McA cells appearing much more insulin sensitive than the other two cell types." (PMID 36615698, 2022). "Insulin increases LDL-R activity in human hepatoma cells whereas it increases the PCSK9 and LDL-R degradation in hepatoma cells and primary hepatocytes." (PMID 35586340, 2022). "SORBS1 involves in cytoskeleton organization and insulin signaling pathway in human hepatoma cell line." (PMID 33971821, 2021). "Hepatoma cell lines, particularly HepG2 cells, have been previously used to model hepatocytes in glucose metabolism and insulin signaling." (PMID 34946711, 2021). "Isothiocyanates inhibited gluconeogenesis and hepatic glucose-6-phosphatase (G6P) expression in hepatoma cells and improved glucose tolerance and insulin signaling sensitivity." (PMID 34776975, 2021). "Then, a further evaluation found that there was a dramatic improvement in the glucose consumption, glycogen synthesis and the activities of pyruvate kinase and hexokinase when the insulin-resistant-human hepatoma cell line (IR-HepG2) was treated with Tmp." (PMID 34574294, 2021). "For example, Pivovarova and colleagues showed that insulin stimulated an increase in hepatic IDE activity, but this insulin-mediated effect was abolished in the presence of high-glucose levels in hepatocellular carcinoma HepG2 cells." (PMID 34572095, 2021). "As it has been claimed that p110α and p110β have redundant roles in insulin signalling in hepatocytes, we also tried the same experiment using the Hepa 1-6 murine hepatoma cell line." (PMID 34884613, 2021). "Insulin-stimulated Akt phosphorylation in HuH7 human hepatoma cells was improved when ENPP1 expression was silenced using siRNA." (PMID 34208364, 2021). "To examine this possibility, we measured GLDC gene expression in H4IIe rat hepatoma cells after treatment with insulin." (PMID 34342168, 2021). "The results indicate that despite the fact that insulin induced AKT Ser 473 phosphorylation to a similar extent in primary hepatocytes and hepatoma cells GSK phosphorylation was significantly increased by insulin only in primary hepatocytes." (PMID 32694512, 2020). "Insulin also stimulated the promoter activity of Angptl8, including the consensus binding motif for Hnf-1, in hepatoma cell lines and mouse primary hepatocytes, thereby confirming that the mechanism of insulin stimulation involves Hnf-1 binding." (PMID 32561878, 2020). "Measuring the glucose uptake rate of adipocytes, myoblasts, and hepatocellular carcinoma cells stimulated by insulin in vitro is an effective method to evaluate insulin sensitivity." (PMID 32964053, 2020).
hepatoma (continued). "For instance, insulin stimulation of the PDH complex was blocked by PKC-δ inhibition in Zajdela hepatoma cultured cells." (PMID 33287820, 2020). "Altogether, our data indicate that hepatoma cell lines from different species largely deviate from the original hepatocyte phenotype for insulin signaling, insulin action on glucose production, and protein expression signature." (PMID 32694512, 2020). "Our data from above show that HepG2, Hepa1-6, and McARH7777 hepatoma cells display similarly aberrant insulin signaling and glucose production machinery." (PMID 32694512, 2020). "Hepatoma cell lines also showed defective expression of gluconeogenic enzymes, insulin unresponsive GSK phosphorylation, and marginal glucose production." (PMID 32694512, 2020). "In vitro studies using hepatoma cell lines demonstrate that high concentrations of insulin inhibit SHBG production." (PMID 33139661, 2020). "Serum Adiponectin was significantly lower in patients with hepatocellular carcinoma (p=0.000 ) and it is inversely correlated to tumor size and the number (p= 0.0001).Meanwhile, Insulin Resistance parameters (Fasting s." (PMID 31244307, 2019). "Our in vitro experiments have shown that limiting AKR1D1 expression and activity regulates fundamental metabolic processes within human hepatoma cells that govern hepatic insulin sensitivity, lipid accumulation and carbohydrate metabolism." (PMID 31330134, 2019). "We further investigated the anti-proliferative effects of β-elemene in hepatocellular carcinoma cell HepG2, and β-elemene treatment also led to significant reduction of the insulin-driven cell growth in a dose-dependent manner (P < 0.01)." (PMID 30422809, 2019). "A previous study used PA to treat Huh7 human hepatoma cells for the purpose of establishing an insulin resistant cell model." (PMID 31060494, 2019). "The effects of SFA on glucose metabolism and expression levels of key proteins in the hepatic insulin signaling pathway were evaluated in insulin-resistant human hepatic carcinoma HepG2 cells." (PMID 31137828, 2019). "Phosphorylation of Akt is activated by insulin stimulation, and Elovl6 suppresses Akt phosphorylation in the presence of insulin in mouse hepatoma cells." (PMID 29700319, 2018). "It should also be noted that even though insulin induced PCSK9 expression in rat/mouse hepatoma cells and primary hepatocytes, it exhibited either neutral or inhibitory effect on serum PCSK9 in human subjects." (PMID 30386595, 2018). "We aimed to investigate if murine cell line AML12 and human cell line THLE-2, which are derived from healthy liver cells, are comparable to hepatoma cell line HepG2 for studying acute insulin signalling and expression of gluconeogenic enzymes and hepatokines." (PMID 30355754, 2018). "Insulin treatment in the rat hepatoma cell line and STZ-induced diabetic rats can inhibit the excess expression of BHMT and SAM." (PMID 29951533, 2018). "Human hepatoma HepG2 cells incubated with normal glucose (5.5 mM, NG model), high glucose (33 mM, HG model), or high glucose (33 mM) plus high insulin (10−7 M, HGI model) concentrations were administered with TV LH-1 ePSP (50, 100, and 1000 μg/ml) for 24 hr." (PMID 30024975, 2018). "Human hepatoma (HepG2) cells were first treated with physiological and supraphysiological concentrations of insulin and sugars to mimic the human hepatic overfed state in vivo." (PMID 30131870, 2018). "This led us to observe that the expression of Enpp1 in rat primary hepatocytes and human hepatoma cells is regulated by insulin and glucocorticoid." (PMID 29513794, 2018). "A previous report also indicated that treatment with insulin increased INHBE mRNA expression in the hepatoma cell line in vitro, which is consistent with the results of our study using primary hepatocytes." (PMID 29596463, 2018).
hepatoma (continued). "In this study, the mRNA expression level of Enpp1 was examined in the liver samples of rats going through fasting and refeeding cycles, and in primary rat hepatocytes and human hepatoma cells treated with insulin and dexamethasone." (PMID 29513794, 2018). "This idea is supported by the report in H4IIE hepatoma, in which insulin co-treatment can enhance GH-induced MEK1/2 and ERK1/2 phosphorylation independent of JAK2/STAT5 activation." (PMID 29977227, 2018). "Rat hepatoma cells treated with dexamethasone or cAMP show a marked increase in the expression of C/EBPα mRNA while insulin opposes this effect." (PMID 29566023, 2018). "As the enzymatic activity of ENPP1 seems to be needed for its inhibitory effect on insulin signaling, the suppression of Enpp1 mRNA abundance by insulin in primary rat hepatocytes and human hepatoma cells was expected." (PMID 29513794, 2018). "Based on the study in H4IIE hepatoma, short-term treatment with insulin (up to hours) can enhance GH-induced MEK1/2 and ERK1/2 phosphorylation." (PMID 29977227, 2018). "Using the trans-omic network and the sensitivity and response time data, we identified pathways mediating induced and basal insulin stimulation both in cultured rat hepatoma cells and in rat liver." (PMID 30267682, 2018). "Insulin is reported to increase PCSK9 expression in hepatoma cells and primary hepatocytes, while another study found that insulin decreases PCSK9 expression and secretion from human cell lines." (PMID 28439730, 2017). "Hepatoma cells co-cultured with adipose tissue of HFF exhibited impaired insulin responsiveness compared to NC, and this impairment was also apparent upon exposure to adipose tissue from HFF→NC adipose tissue." (PMID 28360082, 2017). "To study the effects of leptolide in basal and insulin resistance conditions, we have used a human hepatoma cell line (HepG2)." (PMID 28914811, 2017). "Consistent with previous reports, western blot experiments illustrated that insulin decreased ANGPTL3 production in human hepatoma HepG2 cells." (PMID 27620179, 2016). "The LRC-TriCEPS experiment with CTRP3-FLAG protein as ligand and insulin as a control ligand was performed on the H4IIE rat hepatoma cell line." (PMID 27727322, 2016). "Metformin, an insulin sensitizer is known to improve HCV treatment response and has been associated with a reduced risk of developing hepatocellular carcinoma (HCC)." (PMID 27439433, 2016). "Hepatocyte-specific deletion of Pten, a tumor suppressor gene and negative regulator of the insulin signaling pathway, leads to an age-dependent development of hepatocellular carcinoma." (PMID 27893783, 2016). "An experiment with CTRP3-FLAG protein as a ligand and insulin as a control ligand was performed on the H4IIE rat hepatoma cell line." (PMID 27727322, 2016). "In a hepatoma cell line, increasing media glucose concentration for an extended period of time results in attenuated glucose and insulin inhibition of PEPCK expression and enhanced cAMP stimulated PEPCK expression." (PMID 27992582, 2016). "We carried out our studies of SREBP-1c phosphorylation in McA-RH7777 rat hepatoma cells that are known to recapitulate many aspects of insulin regulation of lipid metabolism." (PMID 26589965, 2015). "In the present study, we examined the effects of L-Citrulline (L-Cit) on insulin sensitivity and signaling cascades in rat hepatoma H4IIE cells and SHRSP.Z-Leprfa/IzmDmcr rats." (PMID 26084330, 2015). "To investigate the temporal effects of RTK activation on protein lysine acetylation, we stimulated HepG2 hepatocellular carcinoma cells with 150 nM insulin for 0, 1, 5, and 30 minutes." (PMID 25978619, 2015). "Apigenin and luteolin, added after insulin within 15 min, reversed the Akt phosphorylation during the following 30 min and reduced the basal phosphorylation of Akt in the human hepatocellular carcinoma HepG2 cells." (PMID 26089893, 2015).
hepatoma (continued). "The main result of the present study was that L-Cit increased insulin sensitivity in rat hepatoma H4IIE cells and SHRSP/ZF rats." (PMID 26084330, 2015). "These authors also demonstrated that amino acid restriction increased the abundance of IGFBP-1 mRNA in rat hepatoma cells, stressing the importance of both insulin and protein substrate in the regulation of IGFBP-1." (PMID 25909895, 2015). "We also exposed human hepatocellular carcinoma HepG2 cells to high levels of palmitate, which enhanced endoplasmic reticulum stress-related gene expression and impaired insulin-stimulated Akt phosphorylation (Ser473)." (PMID 26039731, 2015). "The hepatoma cell line was also used to study the influence of the extract on gluconeogenesis, while the pancreatic cells were used to evaluated insulin secretory activity." (PMID 25070239, 2014). "Insulin-stimulated interaction between endogenous IRS-2 and 14-3-3 was observed in rat hepatoma cells and in mice liver after an acute insulin stimulus and refeeding." (PMID 22912850, 2012). "The present study showed that the effective anti-HBV agent clevudine has a negative effect on the copy number and transcription of mtDNA in insulin-releasing cells and hepatoma cells." (PMID 22230186, 2012). "We next examined the effects of clevudine on the levels of mtDNA and RNA in the human hepatoma cell line HepG2, major target cells of insulin action." (PMID 22230186, 2012). "2- Experiments on pancreatectomized animals; treated with pure insulin or total pancreatic extracts, showed that choline in the extract, preserved them from hepatomas." (PMID 21649891, 2011). "When either Q84 or R84 TRB3 full-length cDNAs were transfected in human HepG2 hepatoma cell lines, as compared with control HepG2 cells, insulin-induced Ser473-Akt phosphorylation was reduced by 22% in Q84- and, of note, by 45% in R84-transfected cells." (PMID 21492415, 2011). "Observations in hepatoma cells show that insulin regulates anticatabolic activity by decreasing Ub mediated proteasomal activity." (PMID 21639905, 2011). "On the contrary, recent studies with hepatoma cells have shown that imatinib attenuates insulin-induced phosphorylation of Akt and glycogen synthase kinase-3β (GSK-3β)." (PMID 19693287, 2009). "In this regard, it is noteworthy that in hepatocellular carcinoma cells, IRS-1 over-expression is associated with increased insulin and IGF-1-stimulated growth and survival signaling, in addition to AAH over-expression relative to the normal liver." (PMID 17156427, 2006). "Insulin decreases the level of glucose-6-phosphatase mRNA in the liver and in hepatoma cells and three functionally distinct insulin response elements have been identified." (PMID 15659240, 2005). "Overexpression of LAR downregulates insulin-stimulated cellular responses in hepatoma cells, suggesting that LAR acts as a physiological modulator." (PMID 12698188, 2003). "In addition, NR6A1 was shown to regulate lipid metabolism, insulin-induced proliferation and cell migration in HepG2 hepatocellular carcinoma cells, by acting through AKT/mTORC1 pathway." (PMID 41550951, 2025). "Additionally, hexanoic acid and octanoic acid have shown to favor lipid catabolism as well as maintain an optimal insulin sensitivity during in-vitro study using HepG2 human hepatocellular carcinoma cells." (PMID 41140397, 2025). "Accordingly, we aimed to elucidate whether Fen interferes with insulin signaling and affects hepatoma cell metabolism." (PMID 40070568, 2025). "Additionally, insulin has been shown to upregulate Bcl-xl expression and promote hepatoma cell migration and invasiveness, further exacerbating malignancy." (PMID 40995175, 2025). "HepG2 is a human hepatoma cell line and displays many differentiated hepatic functions, such as TC and TG metabolism, glycogen and bile acid synthesis, the secretion of plasma proteins, lipoprotein metabolism and transport, and insulin signaling." (PMID 39997187, 2025).
hepatoma (continued). "In conclusion, our study demonstrated that miR-5195-3p plays a critical role in insulin-resistant hepatoma cells and might be a potential therapeutic target for liver cancer." (PMID 37328795, 2023). "HepG-2 is a hepatoma cell line widely used to study liver function and hepatoxicity, mostly because they retain several features of differentiated hepatocytes, including insulin-stimulated glycogen synthesis, glutathione-based detoxification and albumin secretion." (PMID 38136171, 2023). "Diet modulates inflammation and insulin response and may be an important modifiable factor in the primary prevention of hepatocellular carcinoma (HCC) and chronic liver disease (CLD)." (PMID 36943385, 2023). "Mechanistically, we further demonstrated that celecoxib abrogated the activation of Akt/mTOR signalling in insulin‐stimulated hepatoma cells, followed by the reduction of downstream lipogenic proteins at the post‐transcriptional level in chronically insulin‐treated cohorts." (PMID 35713152, 2022). "Alternatively, this might be attributed to differences between primary hepatocytes and hepatoma cell lines, which display several disparities in their signaling and metabolic response to insulin stimulation." (PMID 35740032, 2022). "Mainly The glucose metabolism process and the development and differentiation of precursor adipocytes were regulated of miR-15a by inhibiting the formation of insulin, and miR-20b-5p promoted hepatocellular carcinoma cell proliferation, migration and invasion by down-regulating CPEB3." (PMID 36514049, 2022). "Although insulin has been well established to regulate gene expression through other pathways such as the Ras signaling pathway, we proposed in this study a novel mechanism by which insulin regulates gene expression through p-PDHA1 along with PKM2 in hepatocellular carcinoma HepG2 cells." (PMID 35740278, 2022). "First studies showed that reduced CEACAM1 expression by mRNA transfection in H4-II-E rat hepatoma cells decreased receptor-mediated insulin internalization and degradation, and CEACAM1 phosphorylation regulates receptor-mediated insulin uptake and its degradation." (PMID 35163746, 2022). "AKT‐transfected and insulin‐stimulated human hepatoma cells were used for the in vitro experiments." (PMID 35713152, 2022). "However, the role of p-PDHA1 in hepatocellular carcinoma HepG2 cells due to insulin is poorly understood." (PMID 35740278, 2022). "It is less clear why McA should behave differently to the human hepatoma cell lines, though as discussed later, this may relate to the insulin sensitivity of the cells." (PMID 36615698, 2022). "TRB3 has the tumor-promoting effects of insulin/IGF in hepatocellular cancer cells." (PMID 34906150, 2021). "However, in non-transformed cells, such as 3T3-L1 fibroblasts and adipocytes, only p110α inhibition reduced insulin signalling, while a dependency to p110δ or p110β was only observed in hepatoma or in leukaemia cells." (PMID 34884613, 2021). "Furthermore, V. baillonii exert insulin-mimicking effects by inducing phosphorylation of Akt and inhibit Pck1 mRNA levels in hepatoma cells." (PMID 34899339, 2021). "Additionally, it has also been shown that insulin rises hepatic microsomal PTP-1B activity in rat hepatoma cells." (PMID 35002743, 2021). "Therefore, in our research we focused on the influence of vitamin K2 on insulin resistance in hepatocellular carcinoma cells by influencing the sphingolipid pathway." (PMID 34204938, 2021). "However, a direct comparison of insulin action in primary hepatocytes and in hepatoma cell lines is needed to validate this model and to better understand liver cancer." (PMID 32694512, 2020). "Finally, insulin dose response analysis showed that the three hepatoma cell lines displayed an overall normal insulin-sensitivity for IRβ and AKT Ser 473 phosphorylation." (PMID 32694512, 2020). "Most importantly, insulin action in hepatoma cell lines remains largely uncharacterized." (PMID 32694512, 2020).